MEIS2 (Meis homeobox 2)
Diseases named in the same sentence as MEIS2 in open-access papers (continued):
Sharing a sentence is not in itself a finding about the gene and the disease.
tumor (continued). "Overexpression of Meis1 and Meis2 could induce tumor progression." (PMID 33402862, 2020). "C0 TNFRSF18+ TCs were found in all three tissues, C1 DAPL1+ TCs and C4 MEIS2+ TCs were more common in both normal and tumor tissues overall, and C2 SLC40A1+ TCs were most common in one of the tumor samples." (PMID 40612060, 2025). "The neuroblastoma dependency factor MEIS2, together with ASCL1, was identified as a candidate tumor-initiating factor and shown to be a novel core regulatory circuit member in adrenergic neuroblastomas." (PMID 34638267, 2021). "As a result of the dysregulation, other proteins like MEIS1, MEIS2, TPM1, and ZEB1, which are putative tumor suppressors, are affected." (PMID 24391925, 2013). "These correlative findings provide support to a tumor-suppressive role for MEIS1 and MEIS2 in PrCa." (PMID 32553107, 2020). "Here, we found that MEIS2 can regulate the expression level of IL10 to affect the infiltration of myeloid cells, which may be helpful to understand why IL10 facilitates the formation of immunosuppressive niche in tumor." (PMID 38711262, 2024). "In PC, there is no tumor aggression in patients with high Meis1 and Meis2 expression." (PMID 33402862, 2020). "This is unlikely, however, given the phenocopied tumor suppression phenotype, high degree of homology between MEIS1 and MEIS2 (72.12% similarity), and previously published data demonstrating that knockdown of both MEIS1 and MEIS2 is required for increased PrCa cell line aggression in vivo." (PMID 32553107, 2020).
adenocarcinoma (1 paper, 2009). A common cancer characterized by the presence of malignant glandular cells. "Another finding of our study was the remarkable regulation of hox genes in adenocarcinoma, for example Hoxa5, Hoxb5, Meis1 and Meis2." (PMID 19812696, 2009).
Respiratory diseases (1 paper, 2015). "Another example, topological module 11, with 4 genes, contains MEIS1, MEIS2 and PBX1, which are disease genes associated with Cardiovascular, Neurological, Psychiatric, Endocrine and Respiratory diseases, and these were also defined as a disease module." (PMID 26399914, 2015).
MEIS2 also shares sentences with these, for which no sentence is quoted: glaucoma (3 papers); intellectual impairment (3); acute myeloid leukemia (2); autism (2); neurodevelopmental disorder (2); schizophrenia (2); acute lymphoblastic leukemia (1); attention deficit-hyperactivity disorder (1); autosomal dominant disease (1); benign prostatic hyperplasia (1); bipolar disorder (1); cardiac septal defects (1); cleft lip (1); congenital heart defects (1); craniosynostosis (1); dementia (1); development (1); ductal carcinoma in situ (1); epilepsy (1); hand-foot-genital syndrome (1); heart malformations (1); hematological disorders (1); infection (1); Kabuki syndrome (1); KBG syndrome (1); monoclonal gammopathies (1); Myhre syndrome (1); nail-patella syndrome (1); neurological disorders (1); neutropenia (1).
A further 4 diseases each share a sentence with MEIS2 in 1 paper.